TNF (tumor necrosis factor)
Diseases named in the same sentence as TNF in open-access papers (continued):
Sharing a sentence is not in itself a finding about the gene and the disease.
COVID-19 (continued). "Studies indicate that IL-6, TNF-α, and IFN-γ has become a significant feature of COVID-19 patient deterioration." (PMID 36034662, 2022). "According to the results of cytoscape, the targets of JFBDS for treating COVID-19 mainly contained EGFR, PIK3CA, lymphocyte-specific protein tyrosine kinase (LCK), mitogen-activated protein kinase 1 (MAPK1), MAPK3, MAPK8, STAT3, TNF, IL2 and RELA." (PMID 35165507, 2022). "TNF-α, IL-6, IFN-γ, IL-18, IL-15, IL-1α, IL-1β, and IL-2 are among the most highly upregulated pro-inflammatory cytokines in COVID-19." (PMID 36034662, 2022). "The findings showed that compared to healthy controls, patients with COVID-19 had significantly higher levels of interleukins 1α, 2, 6, 7, 8, 10 and 15, CRP, SAA, ICAM-1, VCAM-1, CXCL10, CCL3, CCL26, IFN-γ, TNF-α, bFGF, PlGF, and Flt-1." (PMID 35958594, 2022). "The key perpetrating pro-inflammatory cytokines which were targeted to manage the symptoms of COVID-19 are IL6 and TNF-α." (PMID 36386162, 2022). "The elevated levels of TNF α, IL-1RA, IL-6, IL-8, IL-10, IP-10, G-CSF and FGF-2 in both patient groups with COVID-19 in our study coincided with previously published studies." (PMID 36012146, 2022). "MAS cytokine storms exhibited higher IL-6, IL-18, IFN-γ, TNF-α, and CXCL9 than severe COVID-19, with IFN-γ, IL-18, and CXCL9 being significantly lower in COVID-19." (PMID 35401519, 2022). "SDE miRNAs in COVID-19 patients were significantly correlated with proinflammatory cytokines such as IL-6, IL-12, IP10, and TNFα, while healthy and infected patients showed different correlation patterns (respectively)." (PMID 35130828, 2022). "Among the cytokines analyzed, those that correlated with a worse prognosis of COVID-19 were resistin, IL-6, IL-8, IL-15, MCP-1 and TNF-α." (PMID 35330391, 2022). "In our study, both TNF-α and IFN-γ, which are critical for innate and adaptive immunity against viral infections, were found to be significantly elevated in tears from COVID-19 patients with active viral infection." (PMID 35508669, 2022). "The pro-inflammatory cytokine TNF-α-induced release of NOX also contributed to local oxidative stress and endothelial dysfunction during COVID-19." (PMID 35741101, 2022). "A total of 27.77% patients treated by anti-IL23, 24.7% of patients treated by anti-TNF and 23.88% of patients treated by anti-IL17 were positive for COVID-19." (PMID 36016267, 2022). "Single-cell RNA sequencing (scRNA-seq) shows classical monocytes as the primary source of cytokines and chemokines in severe COVID-19, such as CCL2, CXCL8, IL-6, TNF-α." (PMID 35401519, 2022). "The results of RNA-sequencing analysis show that several inflammatory factors, including IL-6, TNF, CXCL8, CXCL2, CXCL3, CXCL10, CXCL11, and NF-κB were upregulated, which is consistent with the clinically observed phenomenon in COVID-19 patients." (PMID 36578545, 2022). "Besides, the targets of the main compounds of JWHLGJD are also enriched in pathways related to inflammation, including TNF signaling pathway and coronavirus disease (COVID-19), suggesting that JWHLGJD may act on a variety of cytokines anti-inflammatory and have an effect on CRA." (PMID 35899228, 2022). "In the serum of most COVID-19 patients, the levels of proinflammatory cytokines, including IL-1β, IL-2, IL-6, IL-8, IL-17, G/GM-CSF, MCP1, CCL3 and TNF, are significantly elevated, which is considered a cytokine storm." (PMID 35450063, 2022). "Inflammation is the major pathological response of the body after SARS-CoV-2 infection, in which elevated cytokine levels, such as IL-1β, IL-6, TNF-α, NOS2 and CCL2 are often observed in COVID-19 patients." (PMID 35897044, 2022). "The reduced antibody response to COVID-19 vaccine is likely due to the well-known effect of the CTLA-4-Ig and TNF-α inhibitors on the reduction of the frequency of MBCs in the human peripheral blood." (PMID 35309297, 2022).
COVID-19 (continued). "Recent studies based on in vivo mouse experiments and scRNA-seq analyses of COVID-19-affected lungs have highlighted the role of the IFN-γ-induced inflammatory macrophage phenotype and the synergistic effect of IFN-γ and TNF-α in severe COVID-1938,39." (PMID 36229591, 2022). "For instance, patients with COVID-19 who were admitted in the intensive care unit (ICU) showed a higher abundance of main proinflammatory cytokines, such as TNFα, IL-2, IL-7, IL-10, MCP1, MIP1A, G-CSF, and IP10 in comparison with non-ICU patients." (PMID 35342407, 2022). "In our study, inflammatory cytokines TNF-a, C-Reactive Protein (CRP), and Interleukin 6 (IL-6) significantly differed between patients with moderate and severe COVID-19, indicating their potential as parameters for severity." (PMID 36556051, 2022). "The generation of NOX-dependent ROS elevates TNF-α, transforming growth factor-beta 1 (TGF-β1), ATII, and plasminogen activator inhibitor-1 (PAI-1), all of which are increased in COVID-19 patients." (PMID 35639261, 2022). "Together, these results support the role of TNF and IFN-γ synergism in driving COVID-19 disease progression in cytokine storm syndromes." (PMID 36419185, 2022). "The other PI3K/AKT signaling pathway stimuli which have been increased in COVID-19 patients are inflammatory cytokines, including IL-6, IL-1, TGF-β, and TNF-α." (PMID 35016612, 2022). "Patients with COVID-19 appear to have delayed IFN responses that results in upregulation of the cytokines IL-6, IL-7 and TNF-α." (PMID 35601440, 2022). "Molecular docking suggested that active ingredients (including: licopyranocoumarin, Glycyrol and 3-3-Oxopropanoic acid) in LHQW played a role in treating COVID-19 by acting on CSF2, CXCL8, CCR5, NLRP3, IFNG and TNF." (PMID 36506032, 2022). "STRING database was used to analysis core intersection targets of LHQW and COVID-19, 13 core protein targets (including: NLRP3, TNF, CSF2, IFNG) were obtained by setting confidence degree (confidence degree>0.95)." (PMID 36506032, 2022). "Post-COVID-19 individuals show continued perturbation of proteins related to maintenance of the ECM and TNF signaling." (PMID 36405747, 2022). "Glutamine supplementation reduced the hospitalization period of COVID-19 patients, reduced serum levels of interleukin-1 β, hs-CRP and tumor necrosis factor-α, and increased appetite." (PMID 35406806, 2022). "In fact, many of the components of the cytokine storm described in COVID-19 such as IFN-γ, IL-1β, IL-6, IL-17, and TNF-α can directly induce SkM fiber proteolysis and decrease protein synthesis." (PMID 35625805, 2022). "Survivors of COVID-19 have a reduced brachial artery FMD, which is inversely correlated with increased serum concentration of TNF-α." (PMID 35237624, 2022). "Throughout the progression of COVID-19, the cytotoxic effector molecules in NK cells significantly decrease whereas those of IFN-γ and TNF-α increase." (PMID 36275702, 2022). "In contrast, we found that plasma IL-6, IFN-α, IFN-γ, IL-1β, TNF-α, IL-10, IP-10, MIG and MCP-1 levels were significantly higher in severe COVID-19 compared to healthy controls." (PMID 35422799, 2022). "The antigen-specific T cell response in actively infected COVID-19 patients was predominated by a Th1 phenotype with a significant increase in cytokines, such as IFN-γ, TNF-α, and IL-2 by V3." (PMID 36298628, 2022). "In this context, proinflammatory factors such as IL-1b, IL-6, TNF-a, MCP-1, and aldosterone are elevated in COVID-19 patients." (PMID 35867189, 2022). "According to the preceding discussion, elevated and persistent IL-6, TNF-α, and PAI-1 levels in severe COVID-19 patients potentially generate a vicious cycle of inflammatory response and thrombosis." (PMID 35784318, 2022). "Among the enriched significant pathways, the Coronavirus disease-COVID-19-related pathways is the most significant pathway which involved most of the hHub-DEGs notably, CXCL8, EGFR, IL6, JUN, MAPK1, STAT3, TNF, and UBA52." (PMID 36016137, 2022).
COVID-19 (continued). "Collectively, all the cytokines and chemokines contribute to COVID-19 immunopathology, yet IL-6, IFN, IL-17, TGF-β, TNF-α, and CXCL10 are believed to have major roles in the lung pathogenesis post-SARS-CoV-2 infection." (PMID 35062368, 2022). "Both TNC and FGB induce release of pro-inflammatory cytokines via NF-κB signaling, leading to the presence of TNF-α, IL-6, and chemokine CCL5 upon exposure of hepatocytes to exosomes from COVID-19 patients." (PMID 36077138, 2022). "A recent study indicated that as COVID-19 progresses into later stages, there is a shift from IFN dominance to TNF-α." (PMID 36297092, 2022). "Currently, host response biomarkers used for predicting COVID-19 severity include proinflammatory cytokines (IL6, TNF, IL8, etc.), inflammatory markers (CRP, procalcitonin, and ferritin, etc.), neutrophil/lymphocyte ratio, and lymphopenia." (PMID 36741372, 2022). "In patients with MIS-C, it has been identified the cytokine storm with high concentrations of IL-1β, IL-6, IL-10, TNF-α, and especially IFN-γ, as an antiviral cytokine, comparatively to healthy controls or the children with acute COVID-19." (PMID 35887067, 2022). "COVID-19 patients have high levels of pro-inflammatory cytokines and chemokines such as IL-1β, IL-2, IL-6, IL-7, IL-10, IFN-γ, TNF-α, G-CSF, CCL2, and CXCL10." (PMID 35782361, 2022). "Natural killer (NK) cells from ambulant COVID-19 patients showed increased production of IFN-γ, whereas NK cells from patients with severe COVID-19 produced only low levels of IFN-γ and TNF." (PMID 36129445, 2022). "In particular, the plasma levels of some inflammatory proteins including tumor necrosis factor (TNF) and interleukin-6 (IL-6) were significantly increased in patients with severe COVID-19." (PMID 35283772, 2022). "In order to improve and simplify the efficacy of prediction and diagnosis of CU, especially COVID-19-related CU, we identified three key genes (FCGR3A, CCL3, and TNF) from hub genes by the machine learning LASSO regression analysis." (PMID 36531995, 2022). "In the peripheral blood of COVID-19 patients, the ability of NK cells to produce cytokines, such as IL-2, IFN-γ, and TNF-α, is reduced." (PMID 35625739, 2022). "In particular, COVID-19 moderate patients and recovered individuals from severe disease, when compared to HD, reported higher percentages of IFN-γ+IL-2+TNF+, IFN-γ+TNF+ and IL-2+TNF+ within CD4+ T cells." (PMID 35887351, 2022). "Hadjadj and colleagues demonstrated that IFN-I signaling was highly dysregulated in severely or critically ill COVID-19 patients, as indicated by low IFN-I and ISGs levels, despite increased levels of TNF-, IL-6-, and NF-κB-driven inflammatory responses." (PMID 36298629, 2022). "Only the mixture of TNF-α and IFN-γ induces cell death characterized by inflammatory cell death PANoptosis in Patients with COVID-19." (PMID 35663983, 2022). "A recent study using artificial intelligence techniques revealed that genes involved in activation of immune pathways (IL-6, TNF, JAK2, IL-1B, SERPINE1, TGFB1, CD8A, and VWF) serve as major hubs in the COVID-19- thrombocytopenia interactomes." (PMID 35372456, 2022). "One of the hallmarks of severe COVID-19 is low levels of IFN-I and high levels of expression of inflammatory cytokines or chemokines such as IL-6 and tumor necrosis factor (TNF)." (PMID 36741390, 2022). "Individuals with severe COVID-19 had a lower number of CD4+ and CD8+ T lymphocytes, as well as increased levels of TNF-, IL-1 and IL-6 in their plasma." (PMID 35054471, 2022). "In a clinical study of 109 outpatients with COVID-19, the magnitude and quality of SARS-CoV-2-specific CD4+ T-cell response showed a shift, from IFNγ-producing cells to TNF-α-producing cells over time." (PMID 36032096, 2022). "COVID-19 is characterized by high levels of pro-inflammatory cytokines and chemokines, including IL-2, IL-7, IL-10, G-CSF, IP10, MIP-1A, MCP-1, and TNFα, especially in patients cared for in ICU." (PMID 36423162, 2022).
COVID-19 (continued). "We also highlight how innate immune sensing and activation can lead to pathology, including how TNF and IFN-γ–mediated PANoptosis can drive cytokine storm and severity in COVID-19." (PMID 36419185, 2022). "Upregulated genes in early COVID-19 mortality included many involved with interferon signaling (e.g., GBP2, ISG15), the NF-κB pathway (e.g., NFKB2, NFKBIA), and TNF-α and IL-1 signaling (e.g., TANK, NOD1, RELA)." (PMID 35446789, 2022). "Time-adjusted differences in serum neopterin, β2M, TNF-α, IFN-γ, IL-4, and IL-2 were seen between the groups of patients with COVID-19, with higher concentrations found in neurosymptomatic patients." (PMID 35604688, 2022). "We focused our study on the key pro-inflammatory cytokines IL-6, TNF-α, IFN-γ and interleukins such as IL-1β because they were shown to be elevated in severe COVID-19 patients with severe disease." (PMID 35651623, 2022). "For example, in severe COVID-19 patients, Nature killer (NK) cells showed a prolonged expression of IFN-stimulated genes (ISGs), while tumor necrosis factor (TNF)-induced genes were observed in mild and moderate disease." (PMID 35581387, 2022). "MMP-7, TGF-β, CCL2, CCL-3, CXCL-10, G-CSF, IFN gamma, IL-10, IL-2, IL-4, IL-6, IL-7, TNF-α, IL-6, and IGF-1 were studied for their correlation to lung involvement in COVID-19 patients." (PMID 36286038, 2022). "Local or systemic cytokine release is typical with COVID-19 and interleukin (IL)-6, IL-1β, and tumor necrosis factor-α (TNF-α) play key roles in the progression and exacerbation pathogenesis of COVID-19." (PMID 36590587, 2022). "In fact, of the 13 most abundant mediators in BAL fluid of severe COVID-19 subjects, 11 were chemokines, with CXCL1 and CXCL8 being 200 times more abundant than IL-6 and TNF-α." (PMID 35812400, 2022). "Our research further displayed that all the key genes (CCL3, TNF, and FCGR3A) were statistically related to central infiltration cells (e.g. mast cells and macrophages M0) in CU and COVID-19." (PMID 36531995, 2022). "Besides the direct impact of COVID-19 on the myocardium, another mechanism is possible via the systemic release of various pro-inflammatory cytokines such as interleukine-1 and 6, interferon gamma, macrophage inflammatory protein-1A, and tumor necrosis factor-alpha." (PMID 35740252, 2022). "In addition, the enrichment results showed that the pathogenic processes of RA, AS and GA were all related to the targets of TNF, IL-6, IL-1β and part of the Coronavirus disease signaling pathway, and there were some common pathogenesis, targets and biological processes with COVID-19." (PMID 35935817, 2022). "Besides IL-6, IL-1 and TNF-α could be a predictor of cytokine storm and COVID-19 progression." (PMID 36111104, 2022). "Our results show a statistically significant decrease in TNF-α levels in serum, PBMCs, and neutrophils of COVID-19 ICU patients compared with healthy controls, suggesting an immunomodulatory effect of SARS-CoV-2 on TNF-α production of PBMCs and neutrophils." (PMID 36363785, 2022). "The percentage and counts of immune-suppressive monocytes (mo-MDSCs) identified as CD14+ HLA-DR− monocytes were higher than normal values in severe COVID-19+ patients, independently from the amount of IL-6, IL-1β, IL-17A, TGF-β, TNF-α and IFN-γ." (PMID 35508575, 2022). "Similarly, the concentrations of IL-6, IL-8 and TNFα correlated with the surface expression of CD11b and CD66b in the pooled analysis, whereas only IL-8 and TNFα (but not IL-6) correlated with the percentage of CD49d+ neutrophils when the COVID-19 and Control groups were combined for analysis." (PMID 36466824, 2022). "Its inhibition leads to the reduction of inflammatory cytokines and chemokines, such as TNFα, IL-1, IL-6 and MCP-1, which are thought to be primarily involved in exuberant systemic inflammatory responses in COVID-19 patients." (PMID 35164139, 2022).
COVID-19 (continued). "In convalescent mild and severe COVID-19 patients, a high production frequency of double- and triple-positive IFN-γ–, TNF-α–, and IL-2–producing CD4+ T-cells has been detected." (PMID 36389664, 2022). "Regarding the disease activity and IBD medication, most of the patients diagnosed with COVID-19 were in remission and the majority had been treated with 5-ASA alone, followed by anti-TNF-α antibodies." (PMID 35089397, 2022). "Severe COVID-19 manifested as ARDS with elevated pro-inflammatory cytokines, involving TNF-α, IL-6, IL1B, and CCL2." (PMID 35227280, 2022). "Initial studies in Wuhan, China showed elevated IL-1β, IL-7, IL-8, IL-9, IL-10, FGF, G-CSF, GM-CSF, IFN-γ, IP-10, MCP-1α and 1β, MIP-1, PDGF, TNF-α, and VEGF concentrations in COVID-19 compared to uninfected individuals." (PMID 35401519, 2022). "In COVID-19, GM-CSF activates CD14+ CD16+ monocytes to produce pro-inflammatory cytokines such as IL-6 and TNF-α, further worsening the cytokine storm." (PMID 36111104, 2022). "As an immune response to viral infection, proinflammatory cytokines and chemokines such as IL-6, IL-1, IL-18, TNF, granulocyte-colony stimulating factor (GCS-F) have been detected at high levels in COVID-19 patients." (PMID 34590796, 2021). "dsRNA leads to cellular release of TNF-α and, as reported recently, of TNF-α and IFN-γ, the main drivers of the cytokine storm and cell death occurring in severe forms of COVID-19." (PMID 34887937, 2021). "According to recent reports, a similar immunopathologic lesion is described in severe COVID-19 cases, with enriched macrophages in lungs and elevated cytokines such as IFN-γ, IL-1, IL-6, TNF, and IL-18 in blood, accelerating the collapse of immune homeostasis." (PMID 33397398, 2021). "Our COVID-19 patients had significantly higher levels of IL-1β, IL-1Ra, IL-10, IFN-α2, IL-6, IL-18, and TNF-α than HC." (PMID 34367188, 2021). "Conversely, in non–COVID-19 controls, most SARS-CoV-2–reactive CD4+ T cells were distributed between triple functional cells (IL-2+IFN-γ+TNF-α+) and cells coproducing IFN-γ and TNF-α." (PMID 33945513, 2021). "C3a, C5a, and factor P (properdin), as well as interleukin (IL)-1β, IL-6, IL-8, tumor necrosis factor (TNF)-α, and IgM antibody levels, were higher in critical COVID-19 patients compared to mild COVID-19 patients." (PMID 34276659, 2021). "An increase of HPG, CXCL9, CXCL10, IL-6, MCP-3, TNF and EN-RAGE has also been experimentally detected in patients with severe COVID-19." (PMID 34335580, 2021). "In particular, TNF and IFN-γ highly upregulated in patients with COVID-19, are critically involved in this process." (PMID 34201847, 2021). "In this study, we investigated in vitro the potential involvement of anti-TNF-α therapy in the cellular entry of SARS-CoV-2 and the development of COVID-19." (PMID 34025650, 2021). "Specifically, we demonstrate that pre-infection ability of T cells to express the pro-inflammatory cytokine TNF correlated with more severe virologic outcomes, as has been demonstrated as well for SARS-CoV and COVID-19." (PMID 33513210, 2021). "The cytokine storm syndrome in COVID-19 patients is mainly characterized by the IL-1 family, IL-6, and TNF-α, among which the serum TNF-α level is negatively correlated with T cell function by downregulating the expression of co-stimulatory molecule CD28." (PMID 33808998, 2021). "In both moderate and severe COVID-19 patients, the average concentrations of IL-4, IL-6, IL-10, CCL2, IFN-γ, and TNF-α (P<0.05) were higher than those in healthy donors." (PMID 34489974, 2021). "Elevated serum levels of inflammatory cytokines, including interleukin (IL)-2, IL-4, IL-6, IL-7, IL-10, tumor necrosis factor (TNF), and interferon (IFN)-γ, have been reported in severe COVID-19 patients." (PMID 34959657, 2021).